POMC (proopiomelanocortin)
Diseases named in the same sentence as POMC in open-access papers (continued):
Sharing a sentence is not in itself a finding about the gene and the disease.
Obesity (continued). "In accordance with their role in anorexic signaling pathways, mutations in the MC4R and POMC genes, which encode the melanocortin 4 receptor and pro-opiomelanocortin, respectively, result in hyperphagia and obesity in humans and rodents." (PMID 28592656, 2017). "Deletion of MC4R produces obesity and hyperphagia; furthermore, the most common syndromic cause of obesity, Prader–Willi, occurs in part due to reduced cleavage of POMC." (PMID 28572791, 2017). "Bi-allelic SNVs of leptin (LEP), leptin receptor (LEPR), and pro-opiomelanocortin (POMC) are also associated with hyperphagic obesity." (PMID 28859103, 2017). "Altogether, these results suggest that the depletion of PC in POMC neurons causes hyperphagia-induced obesity." (PMID 28913352, 2017). "Proopiomelanocortin (POMC) deficiency causes severe monogenic obesity that begins at an early age, adrenal insufficiency, red hair, and pale skin." (PMID 28228747, 2017). "Collectively, these data suggest that regulation of POMC and of molecular components of POMC-expressing cells constitutes an important underlying mechanism of obesity in these ciliary mutants." (PMID 27482817, 2016). "Sequencing of candidate genes for obesity in Labrador retriever dogs identified a 14 bp deletion in pro-opiomelanocortin (POMC) with an allele frequency of 12%." (PMID 27157046, 2016). "Further, ablation of the complex B genes, Ift88 or Kif3a, either during adulthood or specifically in POMC-expressing cells of mice, causes hyperphagia, obesity and hyperleptinemia." (PMID 27482817, 2016). "Even though some studies showed an associationbetween POMC rs28932472 and early age of obesity onset in children andadolescents, there is little information about the phenotypes associated with thisSNP." (PMID 25923461, 2015). "Consistent with a pivotal role of the melanocortin system in the control of energy homeostasis, disruption of the POMC gene causes hyperphagia and obesity." (PMID 25999818, 2015). "This phenomenon is compatible with the role of BBS in cilia function, as abrogating cilia in POMC neurons increases food intake and causes obesity in mice." (PMID 25825681, 2015). "In humans, obesity can result from genetic deficiencies which produce a lack in the leptin receptor, POMC, or MC3/4R." (PMID 25999818, 2015). "Defects in endoproteolytic processing of POMC due to deficiency in PC1/3 or mutations in the POMC gene also cause monogenic severe obesity." (PMID 26120850, 2015). "Three genes, MC4R, LEP and POMC, have been identified through genetic association to confer an increase in obesity susceptibility and are also environmentally responsive to dietary intake." (PMID 25127133, 2014). "In particular, both obesity and aging are associated with rewiring of a principal brain pathway modulating energy homeostasis, promoting reduced activity of satiety pro-opiomelanocortin (POMC) neurons within the arcuate nucleus of the hypothalamus (ARC)." (PMID 25051442, 2014). "The critical role of POMC in the regulation of metabolism has been evidenced by studies showing that in humans, individuals with POMC gene mutations display early-onset obesity." (PMID 25538630, 2014). "More recently, increased mTOR signaling was associated with elevated KATP channel activity in arcuate POMC neurons resulting in the cellular inhibition of arcuate POMC neurons concomitant with age-dependent obesity." (PMID 23734095, 2013). "The observation that deletion of the MC4R results in a phenotype that is a virtual carbon copy of POMC-deficient mice (including late onset of obesity and diabetes) strongly supports this idea." (PMID 23543895, 2013). "Mutations that affect processing or lead to loss of expression of the POMC gene also cause obesity in mice and humans." (PMID 23341784, 2013).
Obesity (continued). "Two functionally relevant SNPs, originally identified in different PCSK1 alleles of a female patient with childhood early onset obesity, are associated with abnormal glucose homeostasis, and elevated plasma proinsulin and POMC levels." (PMID 23964269, 2013). "Genetic disruption of AMPK specifically in POMC or AgRP neurons causes obesity or resistance to obesity, respectively, while the neurons themselves maintain the ability to respond to insulin and leptin but not glucose." (PMID 23550218, 2013). "Additional studies will be required to determine the contribution of POMC neurons to these effects and the functional significance of the decline in POMC cell number in aging-associated obesity." (PMID 22319636, 2012). "Functional studies are needed to elucidate the shared or specific molecular mechanisms by which POMC variation influences the susceptibility to SD and/or obesity." (PMID 23028917, 2012). "We propose that any mechanism that increases SOCS3 protein expression beyond a certain level in POMC neurons will cause long-term leptin resistance in those cells and eventually to obesity." (PMID 22276206, 2012). "Risk of substance dependence (SD) and obesity has been linked to the function of melanocortin peptides encoded by the proopiomelanocortin gene (POMC)." (PMID 23028917, 2012). "Mutations in neuropeptide precursors, such as proopiomelanocortin (POMC), have been linked to obesity." (PMID 23189047, 2012). "Overnutrition-related metabolic inflammation in the hypothalamus, specifically in POMC neurons of the arcuate nucleus, was found to underlie the development of obesity-related hypertension in mice." (PMID 22328600, 2012). "Various point mutations of the POMC gene have also been shown to increase the risk of obesity in carriers." (PMID 21860632, 2011). "This strongly suggests that the loss of one copy (haploinsufficiency) of the POMC gene predisposes to obesity." (PMID 21860632, 2011). "HIF loss-of-function in POMC neurons can cause overeating and weight gain to promote obesity development, while HIF gain-of-function can provide strong therapeutic benefits against obesity (and related diseases)." (PMID 21814490, 2011). "Genetic approach was then employed to develop conditional knockout mice with HIF inhibition in POMC neurons, revealing that HIF loss-of-function in POMC neurons impaired hypothalamic glucose sensing and caused energy imbalance to promote obesity development." (PMID 21814490, 2011). "Mice models of progressive loss of hypothalamic POMC neurons or hypothalamic neurodegeneration develop obesity and energy balance defects." (PMID 21589937, 2011). "Loss of function mutations of POMC gene typically results in adrenal insufficiency, obesity and red hair." (PMID 21860632, 2011). "Mutations of POMC should be considered in individuals with severe early onset obesity and adrenal insufficiency even when they lack the typical pigmentary phenotype." (PMID 21860632, 2011). "Taken together, HIF loss-of-function in POMC neurons causes positive energy balance in favor of obesity development." (PMID 21814490, 2011). "The classical clinical triad described with POMC mutations includes early onset obesity, hypocortisolism and red hair." (PMID 21860632, 2011). "Heterozygosity for deleterious coding mutations in MC4R or POMC has been associated with a non fully penetrant form of obesity, whereas partial LEP or LEPR deficiency has been associated with a higher percentage of body fat mass." (PMID 22043164, 2011). "Although CART deficiency does not appear to influence energy balance, there is clear evidence that POMC peptides play a critical role in feeding behaviour with both POMC deficient mice and humans developing hyperphagia and obesity." (PMID 17448988, 2007). "Mutations in the POMC gene lead to severe early-onset obesity and increased food consumption." (PMID 41723268, 2026).
Obesity (continued). "This could enable in vitro modeling of hunger-suppressing POMC+ hypothalamic neurons; their importance in vivo is underscored by the severe obesity of POMC-deficient humans and mice." (PMID 40631129, 2025). "Setmelanotide is another anti-obesity medication; however, it has been approved only for three ultra-rare genetic disorders that cause obesity: Pro-OpioMelanoCortin (POMC) deficiency, Proprotein Convertase Subtilisin and Kexin type 1 (PCSK1) deficiency, and LEPtin Receptor (LEPR) deficiency." (PMID 40806889, 2025). "Setmelanotide has also been approved for the treatment of obesity and hunger due to genetic disorders such as Bardet-Biedl syndrome, pro-opiomelanocortin (POMC) loss-of-function, including proprotein convertase subtilisin/kexin type 1 (PCSK1), and LEPR deficiency." (PMID 40297673, 2025). "Similarly, the pro-opiomelanocortin (POMC) locus has been linked to obesity phenotype, and a c.231C > A change has been reported to be subjected to premature obesity." (PMID 40024983, 2025). "The recent approval of Setmelanotide, an MC4R agonist, for treating obesity caused by deficiencies in proopiomelanocortin (POMC), proprotein convertase subtilisin/kexin type 1 (PCSK1), or Leptin Receptor, has heightened scientific interest in the effects of MCRs on feeding and energy balance." (PMID 39974186, 2025). "Heterozygous variations in the POMC gene are relatively common and may contribute to obesity, which is strongly linked to gynecomastia." (PMID 40002676, 2025). "POMC mutations in both transgenic animal models and in humans result in hyperphagia, impairments in glucose homeostasis, decreased energy expenditure and early-onset obesity." (PMID 40283207, 2025). "Moreover, genetic studies further emphasize the heterogeneity of obesity, with variants in POMC and MC4R contributing to severe early-onset forms." (PMID 41333852, 2025). "The importance of the arcuate nucleus POMC system in the control of appetite and satiety is indicated by experimental and clinical observations showing that deficits in some of its components are associated with obesity." (PMID 39129011, 2024). "Homozygous or compound heterozygous mutations of POMC result in early-onset obesity." (PMID 39526054, 2024). "Dysfunction of the POMC gene causes severe early-onset obesity." (PMID 39484290, 2024). "In addition, mutations in the POMC gene and in the PCSK1 gene, which encodes an endopeptidase that plays a critical role in POMC processing, also result in severe forms of obesity." (PMID 39876968, 2024). "We presumed that the reduced low level of Calr detected in the secretome of SIK2-deficient POMC neurons during the early ER stress response may interfere with the proper folding of App in relation to the pathogenesis of obesity and related diseases." (PMID 39329749, 2024). "Similarly, the long-term outcomes of bariatric surgery were evaluated in patients with bi-allelic mutations in known monogenic obesity genes such as POMC, LEPR, and MC4R." (PMID 38469147, 2024). "Surprisingly, POMC-specific OPA1-knockout mice develop obesity at 7 weeks of age and exhibited mitochondrial cristae loss fragmentation, Ca2+ overload, and decreased α-MSH release, but glucose sensing, neuronal activation, and hypothalamic ROS production are not changed." (PMID 37174622, 2023). "Ciliogenesis was disrupted in rodent POMC neurons at embryonic day 10 by conditionally knocking-out Ift88, and the subsequent reduction in dendrite formation and arborization impaired circuit development leading to hyperphagic-associated obesity." (PMID 37064917, 2023). "Some in vitro studies showed that chemical chaperones and a newly FDA-approved drug, Setmelanotide (an MC4R agonist), could be used to treat some monogenic forms of obesity due to POMC, PCSK1, or LEPR deficiency." (PMID 38003551, 2023).
Obesity (continued). "Hence, the phenotype of POMC-associated monogenic obesity is typically characterized by pale skin and red hair, hyperphagia, severe obesity, adrenal insufficiency, and occasionally cholestasis." (PMID 37512517, 2023). "Moreover, specific restoration of leptin receptors in POMC neurons (presumed activation of these neurons) or AgRP neurons (presumed inhibition of these neurons) causes little effects on obesity reversal in db/db mice." (PMID 37069175, 2023). "Therefore, olfaction and alterations in activity of POMC neurons likely contribute to the dysregulation of energy balance and increased obesity in people affected with FMR1 mutations." (PMID 37542065, 2023). "In addition, recent studies have demonstrated a strong association reported between a deletion present in the POMC gene of Labradors and increased body weight and obesity." (PMID 36977247, 2023). "Recent work has investigated whether changes in the function of ArcN NPY or POMC neurons in males with obesity underlie sensitization to the sympathoexcitatory effects of leptin and/or its metabolic partner, insulin." (PMID 36769012, 2023). "Conversely, dysregulated DNA methylation has been implicated in the pathogenesis of obesity because it may lead to leptin resistance through hypomethylation of POMC." (PMID 37899888, 2023). "Another important takeaway from GWAS is the fact that numerous common polymorphisms associated with polygenic obesity in ethnically diverse population have been found in genes like PCSK1, MC4R [43••] and POMC, known to carry rare loss of function variants leading to non-syndromic monogenic obesity." (PMID 37819541, 2023). "In 2020, the Food and Drug Administration (FDA) approved the first treatment involving the MC4R agonist setmelanotide for chronic weight management in adult and pediatric patients at least 6 years of age with obesity due to three rare genetic conditions: POMC, LEPR, or PCSK1 deficiency." (PMID 37571382, 2023). "Multicenter, open, single-arm phase 3 studies were carried out in ten hospitals in Canada, the USA, Belgium, France, Germany, the Netherlands, and the UK in patients with morbid obesity associated with pro-opiomelanocortin deficiency (POMC) or obesity due to leptin receptor deficiency (LEPR)." (PMID 37888071, 2023). "Interestingly, chronic activation of mTOR in POMC neurons caused by aging leads to hyperphagic obesity." (PMID 38027481, 2023). "Importantly, deletion of TrpC5 in POMC neurons leads to obesity in male mice, which is associated with increased daylight feeding and decreased energy expenditure." (PMID 33826123, 2022). "Other loci which have been implicated in severe childhood monogenic obesity include genes of the proopiomelanocortin (POMC), the melanocortin receptor 4 (MC4R), the protein convertase 1/3 (PC 1/3), the single-minded homolog 1 (SIM1), and the brain-derived neurotrophic factor (BDNF)." (PMID 36452324, 2022). "In addition, chronic HFD provoked a reduction in the number of hypothalamic POMC neurons which was associated to weight gain and obesity." (PMID 35603807, 2022). "This sex-specific decrease of POMC neurons probably can be explained by the decrease of phagocytic capacity we found in microglia-InsR-KO males in obesity, as previously it has been demonstrated that impaired microglial phagocytic capacity leads to loss of POMC neurons." (PMID 35328354, 2022). "Such genetic variants in the leptin-melanocortin signaling pathway are the cause of rare genetic diseases of obesity, including proopiomelanocortin (POMC) deficiency and leptin receptor (LEPR) deficiency, which are characterized by early-onset severe obesity and hyperphagia." (PMID 35123544, 2022). "As it is well accepted that HFD induces hypothalamic inflammation even before the development of obesity, inflammation could be the final cause of hypothalamic POMC neuronal loss/inhibition." (PMID 35603807, 2022).
Obesity (continued). "Hence, a deficiency of POMC leads to hyperphagia, lower resting metabolic rate, and resultant severe obesity with red hair and pale skin." (PMID 36232301, 2022). "Genetic variants may be restricted to a small number of breeds, e.g., a 14 base-pair deletion in POMC associated with obesity and food motivation found in Labradors and Flat-coated Retrievers." (PMID 36619947, 2022). "However, the vast majority of POMCCreGFP + cells continue expressing POMC throughout the adulthood and the obesity phenotypes associated with POMCCre-restricted PI3K-Akt-mTOR pathway over-activation are largely explained by inactivation of POMC neurons." (PMID 35490865, 2022). "Since obesity in DicerCKO mice is associated with the loss of the Dicer1 gene both in AgRP and POMC neurons, while miR-15-5p is highly expressed in POMCCre-GFP neurons, we sought to genetically inactivate this microRNA in POMCCre-Cas9-GFP cells during adulthood." (PMID 35873003, 2022). "Several syndromic and monogenic disorders of obesity that have been identified include Prader–Willi syndrome, Bardet–Biedl syndrome, and loss-of-function mutations in the genes encoding for pro-opiomelanocortin (POMC), leptin, leptin receptor (LEPR) or the melanocortin-4 receptor (MC4R)." (PMID 35299971, 2022). "However, this phenomenon also confirms that the increase in high levels of plasma under previous obesity conditions can cause POMC neuron stimulation, which will further induce sympathetic activation." (PMID 36479119, 2022). "Thus, rare variants within this locus impact obesity by making this site susceptible to methylation, which consequently attenuates the expression of POMC, ADCY3 and DNAJC27." (PMID 34207686, 2021). "It has been shown that HEK293 cells are transiently transfect with the mutant melanocortin 4 receptor (MC4R), a rhodopsin-like GPCR expressed in the hypothalamic pro-opiomelanocortin (POMC) neurons and the gene most commonly linked to obesity, which is located on chromosome 18q21.31at an early age." (PMID 34835958, 2021). "Inhibition of microglial activation and inflammation in the ARC may be sufficient to protect against diet-induced hypothalamic inflammation and POMC neuronal loss and prevent obesity." (PMID 34720877, 2021). "Initial reports of hypothalamic neuroinflammation in obesity postulated that neuroinflammation is caused by stress and dysfunction of the feeding circuitry neurons, anorexigenic POMC, and orexigenic NPY, in the arcuate nucleus (ARC), since inflammation was detected specifically in this region." (PMID 34154608, 2021). "Moreover, diet-induced obesity renders VMN SF-1/ARC POMC synapses more susceptible to the inhibitory effects of exogenous N/OFQ in males and hypoestrogenic OVX females." (PMID 33800452, 2021). "Setmelanotide is prescribed for the treatment of rare genetic diseases of obesity caused by certain variants of the genes encoding for pro-opiomelanocortin (POMC), proprotein convertase subtilisin/kexin type 1 (PCSK1), or leptin receptor (LEPR) all of which cause a deficiency of these molecules." (PMID 33670364, 2021). "However, large decreases in POMC neuronal mitochondrial function inhibited hypothalamic fatty acid oxidation and caused obesity." (PMID 33917812, 2021). "In addition, the activation of the IKKβ/NF-κB inflammatory pathway plays an important role in the process of POMC neurons loss, and POMC neurons play an important role in preventing obesity." (PMID 34307371, 2021). "C28F POMC is a mutant prohormone that causes early onset obesity." (PMID 34467852, 2021). "Conversely, deletion of POMC neurons and loss of POMC-derived transmitters result in obesity." (PMID 33849593, 2021). "As case reports continue to accumulate, the POMC deficiency reveals to be a more complex endocrine disorder than initially perceived and goes beyond its characteristic triad of adrenal insufficiency, early onset obesity, and red hair." (PMID 34177811, 2021).